GZMA (granzyme A)
Diseases named in the same sentence as GZMA in open-access papers (continued):
Sharing a sentence is not in itself a finding about the gene and the disease.
tumor (361 papers, 2008 to 2026). "Granzyme A expression has been associated with cytotoxic activity against tumor or virus-infected cells as well as the stimulation of several immune cell types." (PMID 39851522, 2025). "It was shown that GZMA downregulation was associated with poor prognoses, which further implicates GZMA in tumor growth." (PMID 40002821, 2025). "Abundant infiltration of granzyme A‐expressing intraepithelial ILC1s was found to enrich the tumour of chRCC patients and was positively associated with overall survival." (PMID 40801800, 2025). "Correlation analysis showed that among 18 predominant bacterial genera of the tumor microbiome, Acinetobacter and Dietzia were inversely correlated with the abundance of FoxP3+ cells, and Pelomonas was negatively associated with GZMA level." (PMID 39554133, 2024). "Gasdermin B protein is abundantly expressed in epithelial cells of the alimentary tract and highly susceptible to pyroptosis induced by granzyme A. This mechanism is essential for the elimination of gastrointestinal tumor cells." (PMID 36769513, 2023). "In HCC patients, the expression level of GZMA is closely associated with tumor growth, metastasis, and prognosis." (PMID 37884883, 2023). "Collectively, GZMA-F2R communication inefficient induces deficient PD-1 mAb therapy and provide a completely novel immunotherapy strategy for tumor suppression in HCC patients." (PMID 35256589, 2022). "In order to decipher the molecular mechanism underlying the GZMA-F2R communication in tumor suppression, the differentially expressed genes in the low F2R/GZMA expression HCC patients were identified." (PMID 35256589, 2022). "One in vitro study showed that T cells activated by a T-BsAb utilized perforin and granzyme A/B to cause necrosis and apoptosis, respectively, when bridging tumor cells." (PMID 34832954, 2021). "Meanwhile, CD8A and GZMA also had similar expression variants in several tumor types such as COAD, SKCM, STAD, KIRC, and THCA." (PMID 33585244, 2020). "Proteins associated with tumor regression including granzyme A (GZMA) and Th1 markers such as the C-X-C motif chemokine ligand family (CXCL9, CXCL10, CXCL11) and interferon gamma (IFNG) mirrored the checkpoint inhibitor decreases seen in tissue during single agent pembrolizumab therapy." (PMID 36572780, 2022). "Moreover, the molecular mechanism underlying the GZMA-F2R communication in antitumor immunotherapy and its role in PD-1-suppressed tumor progression were elucidated." (PMID 35256589, 2022). "These included key genes associated with cytotoxic anti-tumor T cell responses (GZMA, GZMB, PRF1), co-stimulation of T cells (CD27, CD28, ICOS), and genes associated with other immune processes, including Type I IFN response (TNF, TNFSF10), as well as T cell exhaustion (CTLA4)." (PMID 36698398, 2022). "Additionally, it has been demonstrated that the lymphocyte-derived granzyme A (GZMA) hydrolyzes GSDMB at Lys229/Lys244 site to cause tumor cell pyroptosis in the same year." (PMID 36119049, 2022). "Therefore, the immunosuppressive tumor microenvironments in patients of the dominant group could be caused by the CD8-Tef-GZMA and CD8-Tef-APOC2 subpopulations." (PMID 36497182, 2022). "Thus, tumour cells that are resistant to caspase-mediated cell death, including GBMs that overexpress Bcl-2, might be more sensitive to granzyme A. IFNγ has also previously been implicated in the modulation of levels of HLA ligands." (PMID 31319548, 2019). "Thus, mice deficient in gzmA, gzmB cluster, or both are more susceptible to infection with herpesvirus, particularly cytomegalovirus, and mousepox, ectromelia virus, but their role in NK cell-mediated tumour rejection has been controversial." (PMID 21853094, 2011). "Cytokine bead arrays quantified IFN-γ, granzyme A, and granzyme B levels to assess anti-tumor immune activation." (PMID 41800236, 2026).
tumor (continued). "MUT tumors showed high tumor mutation burdens with APOBEC-associated kataegis and cytolytic/immune-activation programs with M1 macrophage including upregulation of GZMA, GZMB, and large-scale transition." (PMID 41991965, 2026). "The enhanced secretion of GZMA by CTLs is expected to drive tumor-specific pyroptosis via GSDMB cleavage, further amplifying antitumor immunity in a self-reinforcing manner." (PMID 41576171, 2026). "Single-cell and spatial transcriptomics revealed that ZEB1 ablation promoted tumor pyroptosis by recruiting and activating GZMA+CD8+ T cells in the tumor core through epigenetic upregulation of CXCL16." (PMID 40924501, 2025). "These activatable probes will support downstream activity‐based protein profiling and enable noninvasive imaging of the enzyme activity, offering a powerful means for dissecting the multifaceted biology of GzmA within the tumor immune microenvironment." (PMID 41258732, 2025). "Given GZMA’s high expression in NK cells, we analyzed the interactions between GZMA-enriched NK cells and tumor malignant cells." (PMID 40104502, 2025). "In recent years, CD8+ T cells, as key effector cells of the cytotoxic immune response, have been shown to exert antitumor effects by inducing tumor cell pyroptosis, primarily through release of granzyme A (GZMA) and GZMB." (PMID 40924501, 2025). "Despite its implication in both immune‐mediated tumor cell killing and chronic inflammation, the role of GzmA in the TIME remains incompletely understood." (PMID 41258732, 2025). "Interleukin‐15 (IL‐15) promoted ILC1 granzyme A expression and cytotoxicity, and IL‐15 expression in chRCC tumour tissue positively tracked with the ILC1 response." (PMID 40801800, 2025). "Compared to SLAMF7− DNT, adoptively transferred SLAMF7+ DNT had an increased tumor-infiltrating level, elevated Ki67 expression, and significantly elevated production of cytotoxic molecules, such as granzyme A, granzyme B and perforin." (PMID 41168829, 2025). "Conversely, in the tumour compartment, GZMA, STING and fibronectin displayed a positive correlation with chemotherapy response, while CD80 showed a negative correlation." (PMID 40677104, 2025). "GZMA was significantly more expressed in lymphocytes, especially T cells, indicating its role in the anti-tumor immune response." (PMID 40104502, 2025). "Exogenous overexpression of GSDMB isoform‐3 in murine cancer cells influences immune stimulation with anti PD‐1 immunotherapy, leading to T‐cell/GZMA‐dependent tumor suppression." (PMID 40783818, 2025). "Instead, it was seen that these MVs had FasL, granzyme A, granzyme B, and perforin in their composition, suggesting their role in the anti-tumor apoptotic process." (PMID 40149564, 2025). "In the postinfusion NK cells, NK1 was the dominant subcluster, expressing high levels of cytotoxic effector genes (CST7, SRGN, and GZMA), indicating its key role in tumor cell killing." (PMID 40315330, 2025). "In our study, we performed a complete evaluation of GZMA expression throughout more than one cancer type, revealing tremendous dysregulation in tumor tissues in comparison to everyday tissues." (PMID 39228516, 2024). "For example, GZMA can penetrate tumor cells through perforin-mediated pathways, triggering cell death programs." (PMID 39228516, 2024). "Research findings demonstrated that GZMA released by CD8+TILs can effectively cleave GSDMB within tumor epithelial cells, culminating pyroptosis." (PMID 39030523, 2024). "Granzyme A expression was reduced in both frequency and intensity in CD56dim NK cells from central tumor samples from patients with NSCLC compared with healthy blood controls, hinting at a release of granzyme A by NK cells within the tumor." (PMID 38956379, 2024). "Multiple immune-associated genes such as CD79A, CD3E, CD3D, ZAP70, CXCR6, and GZMA were upregulated in hot tumor regions." (PMID 38803565, 2024).
tumor (continued). "Accordingly, human patients with chRCC were found to have significant tumour infiltration of cytotoxic GzmA-expressing cells that positively correlated with survival." (PMID 38745765, 2024). "Conversely, TCR+ Macrophages can directly eliminate tumor cells using cytotoxic granules, such as GZMA and GZMK." (PMID 38948071, 2024). "GZMA participates in immune monitoring of tumor cells by its expression in cytotoxic T lymphocytes and natural killer cells." (PMID 39228516, 2024). "The release of GzmA/B by CTLs into tumor cells via perforin directly or indirectly triggers GSDM-dependent pyroptosis, resulting in immune activation." (PMID 38987821, 2024). "In this context, the constitutively active STAT6 drives the expression of granzyme A, granzyme B, FasL and IFNγ proteins, which can be critical to donor T cell-mediated anti-tumor (GVT) immunity." (PMID 39796136, 2024). "Specifically, the proportions of COL1A1+ macrophages and GZMA+ macrophages deceased in tumor groups, while CXCL3+ macrophages appeared exclusively in tumor samples." (PMID 39112478, 2024). "CD8+T cells secreting granzyme A (GZMA) can induce pyroptosis in tumor cells by effectively cleaving gasdermin B (GSDMB), which is stimulated by interferon-γ (IFN-γ)." (PMID 39030523, 2024). "Researches have indicated that GZMA can specifically cleave GSDMB at the Lys244 or Lys229 residues in tumor epithelial cells, thereby inducing pyroptosis." (PMID 39030523, 2024). "Patients with low GZMA expression usually have larger tumor burden and malignant cell characteristics, resulting in poorer prognosis." (PMID 37884883, 2023). "The EVs from activated NK cells include a variety of Gzms, such as GzmA and GzmB, which have cytotoxic effects on tumor cells, inhibit cell proliferation, and promote cell death." (PMID 36875082, 2023). "Both activated CD8+ T cells and NK cells show cytolytic activity against tumor cells by secreting several cytolytic molecules, such as granzyme A (GZMA), GZMB, and perforin (PRF1), showing good prognoses in various types of cancers." (PMID 38203530, 2023). "In this study, the perforin, granzyme B, and granzyme A secreted by CTL cells in tumor tissue were evaluated by immunohistochemical staining." (PMID 37529049, 2023). "When ctDNA detection was combined with the level of tumour mutational burden (TMB) and a tumour-derived interferon signature (including HLA-DRA, CXCL9/10/11, GZMA, PRF1, CCR5, IFNG, IDO1 and STAT1), the predictive value of the combined score was enhanced." (PMID 38201222, 2023). "Critically, Granzyme A was able to cleave GSDMB in vivo with enhanced tumour clearance, highlighting the likely reason many cancers downregulate GSDMB in an oncogenic fashion." (PMID 37266429, 2023). "In contrast to trNK cells and CD8+ TRM cells, their non-tissue-resident counterparts (defined as CD49a−CD103−CD16− NK cells and CD49a−CD103−CD8+ T cells, respectively) expressed granzyme A and B less frequently in the tumor center." (PMID 37448786, 2023). "Consistently, the tumor-infiltrating GZMAhigh NK subcluster expressing a high level of cytotoxic genes (GZMA, GZMB, GZMK, GZMM, GZMH, PRF1, and GNLY) and FASL and TRAIL genes was most enriched in the PD-1+SMI group." (PMID 37430270, 2023). "Meanwhile, a kind of chemotherapy drug, Fludarabine, were introduced in to check the relationship between GZMA and anti-tumor effect of the potential drug obtained from this model." (PMID 37464443, 2023). "Granzyme A can induce pyroptotic death against tumor cells with gasdermin B protein, which is expressed abundantly in epithelial cells in the gastrointestinal tract." (PMID 36769513, 2023). "In CD8+ T cells, we observed upregulation of GZMA, which is indicative of effector functions, and CCR7, which is associated with increased homing to the tumor sites." (PMID 36911698, 2023).
tumor (continued). "CD8+TILs can exert anti-tumor functions through several pathways such as the release of GZMA and GZMB, Fas-Fas ligand pathway-mediated apoptosis, and secretion of inflammatory cytokines like IFN-γ and TNF-α." (PMID 37781365, 2023). "By contrast, immunocyte-triggered mouse GZMA can cleave GSDMB3 in tumor xenografts leading to cancer pyroptosis." (PMID 36899106, 2023). "In the present study, cluster mCAF1/2 received immune signals from suppressive T cells (CD8+ exthausted T cells and Treg) through GZMA and its receptor F2R instead, as a potential mediator of tumour microenvironment." (PMID 36855810, 2023). "In the process of cytotoxic lymphocyte killing target cells, cytotoxic lymphocyte-derived GZMA cleaves pore activity, thereby triggering target cell pyroptosis, a molecular mechanism that enhances anti-tumor immunity." (PMID 37620327, 2023). "Recently, GSDMB has been demonstrated to be cleaved by granzyme A from cytotoxic lymphocytes to induce pyroptosis in GSDMB-expressing tumor cells." (PMID 37705753, 2023). "In HBV-related HCC, cytotoxic CD4+ T cells present similar numbers with cytotoxic CD8+ T cells, while they are less effective to eliminate tumor cells due to secreting less cytolytic factors such as granzyme A (GzmA) and granzyme B (GzmB)." (PMID 38090482, 2023). "Further exploring the mechanism showed that GZMA enhanced the inflammatory response and mediated tumor progression by inducing the production of IL6 in macrophages and activating pSTAT3 pathway in cancer cells." (PMID 35464869, 2022). "By measuring perforin (PRF1) and granzyme A (GZMA) gene expression as representative of cytolytic activity (CYT) in tumors we also found that CYT was inversely correlated with tumor stages across all cancer types." (PMID 35237269, 2022). "Inflammasome activation in myeloid cells has recently been implicated in the development of CAR T cell–associated CRS, as a consequence of tumor cell pyroptosis induced by CAR T cell–released granzyme B and granzyme A." (PMID 35503659, 2022). "A study published in 2020 discovered that CD8+ T cells and natural killer (NK) cells boosted tumor clearance via the GSDMB–granzyme A axis." (PMID 35677632, 2022). "In the present study, the GZMA-F2R communication at the LDPRSFLL motif of F2R suppressed tumor progression by promoting the JAK2/STAT1 signal activation-induced apoptosis." (PMID 35256589, 2022). "Differential gene analysis between cluster 2 and cluster 3 confirmed that cluster 2 expressed high tumor-suppressing genes (e.g., GZMA) in tumor." (PMID 36357424, 2022). "Granzyme A (GzmA) was reported to trigger tumor clearance by recruiting NK and CD8+ T cells and induce pyroptosis via cleavage of GSDMB." (PMID 35558555, 2022). "CTL recognizes MHC-I molecules expressed by tumor cells, exerting tumor killing mechanisms through granule exocytosis (granzyme A and B) or death ligand-induced necrosis and apoptosis under the action of chemokines." (PMID 35874717, 2022). "Cytotoxicity-related genes GNLY, NKG7, GZMB and GZMA were downregulated in both tumor-derived CD4+ and CD8+ T cells." (PMID 36506053, 2022). "In the present study, the GZMA-F2R communication promoted JAK2/STAT1 signal-induced tumor suppression both in vitro and in vivo." (PMID 35256589, 2022). "For instance, CD8+ T cells and NK cells in the TME can trigger tumor clearance via the GSDMB granzyme A axis, which is aided by IFN-γ." (PMID 36152052, 2022). "Unfortunately, the GZMA-positive cytotoxic cells were detected mainly in the adjacent tissues, while the tumor cells from the tumor tissues (cluster 5 and 8) were negative for F2R." (PMID 35256589, 2022). "At the same time, our analysis found that PROZ was negatively correlated with genes related to immunotherapy efficacy such as CD8A, CD274 and GZMA, and was also negatively correlated with T-cell infiltration in tumor tissue." (PMID 36140703, 2022).
tumor (continued). "For example, IFNG and genes encoding cytolytic enzymes (GZMA, GZMB and PRF1) were relatively up-regulated in SCLC-I tumors, indicating that SCLC-I tumors are characterized by a high level of tumor-infiltrating lymphocytes with potential cytolytic activity." (PMID 36428693, 2022). "Next, to validate activation of the CD8+ T and NK cells, gene expression analysis of GZMa (granzyme a), GZMb (granzyme b) and Prf1 (perforins) showed a significant increase in tumours of mice treated with RGD4C.TPA.IL15IgK particles." (PMID 35758207, 2022). "In separate research published the same year, CD8+ T cells and NK cells were demonstrated to promote tumor clearance via the GSDMB granzyme A axis." (PMID 35085103, 2022). "Together, these results suggested that the GZMA-F2R communication suppressed the tumor by promoting the activation of JAK2/STAT1 signaling pathway." (PMID 35256589, 2022). "In nodal metastases tumor regions, CD8 and STING were associated with improved OS; however, GZMA was associated with poorer OS." (PMID 35651606, 2022). "In particular, six tumor cytotoxicity-related molecules (GZMA, GZMB, GZMH, IFNG, FASLG, and NKG7) from T cells had significantly higher levels in the BM than in PB." (PMID 40977909, 2022). "Assuredly, perforin delivers GZMA to the cytosol of target cell and suppresses tumor progression in caspase-independent apoptosis." (PMID 35256589, 2022). "Differential analysis of tumour compartments indicated the enrichment of GZMA, STING and fibronectin in responsive patients, while CD80 levels were higher within refractory tumours." (PMID 35083152, 2021). "The infiltrating T cells release granules containing perforin and granzyme A and B which directly kill tumor cells or release other cytokines and chemokines that promote the anti-tumor immune response and alter the tumor microenvironment." (PMID 33796222, 2021). "Another tumoricidal factor, granzyme A, is secreted by cytotoxic T-cells mediating direct tumor cell lysis." (PMID 34200100, 2021). "The expression of TNF, IFN-γ, GZMA, and GZMB was higher in the low-risk group, suggesting a stronger cytotoxicity to tumor cells." (PMID 34616734, 2021). "A recent study reported that cytolytic activity score (CYT) based on granzyme A and perforin expression were hallmarks of T cell infiltration and activation, and high CYT was associated with a more immunosuppressive tumor microenvironment and worse prognosis." (PMID 34094918, 2021). "The present study showed that the pyroptosis genes GZMA, AIM2, and PD-L1 were associated negatively, whereas the risk signature was associated positively with tumor stem cell scores." (PMID 34721986, 2021). "Perforin binds to the surface of target tumor cells, generating pores, and then granzymes, particularly granzyme A and B, enter the target cells through pores and stimulate apoptotic cascades." (PMID 32397120, 2020). "Exposure to TGF-β reduced the expressions of apoptotic activators (such as perforin and granzyme A and B) on cytotoxic T cells that infiltrated the tumor tissues." (PMID 31938023, 2020). "Eosinophils not only regulate T-cell activation but also exert anti-tumor responses through degranulation and secretion of granzyme A as well as TNF-α via their natural killer group 2 member D (NKG2D) binding to NKG2D ligands (NKG2DLs) on tumor cells." (PMID 32499786, 2020). "NK cell-derived exosomes contain FasL, granulysin, perforin, granzyme A and B therefore exerting cytotoxic activity against tumor cells." (PMID 32499786, 2020). "Based on the co-expression correlation between CD274 and CD8A in 29 tumor types, and between GZMA and PRF1 in 32 tumors, we further classified TME into eight groups according to IRGs’ expression level." (PMID 33585244, 2020). "When co-administered with antigen, GzmA acted as a powerful adjuvant for eliciting antigen-specific cytotoxic CD8+ T lymphocytes (CTLs) that protected mice from tumor challenge." (PMID 31293597, 2019).